MMP13 (matrix metallopeptidase 13)
Diseases named in the same sentence as MMP13 in open-access papers (continued):
Sharing a sentence is not in itself a finding about the gene and the disease.
periodontal disease (11 papers, 2013 to 2025). "Fibrous collagenases such as MMP1 and MMP13 have been associated with diabetic complications and periodontal disease." (PMID 39456763, 2024). "MMP-8, MMP-9, and MMP-13 have been demonstrated to be associated with the severity of periodontal disease and are promising candidate biomarkers in oral fluids such as gingival crevicular fluid (GCF), mouthrinse, and saliva." (PMID 30669541, 2019). "In addition, the in vitro MMP inhibition assays were carried out with MMP-9 (92 kDa gelatinase) and MMP-13 (collagenase-3), both known to be associated with periodontal disease and other conditions of connective tissue loss." (PMID 24453415, 2013). "In this context, matrix metalloproteinases, such as MMP-13, stand out for their potent collagenolytic activity and correlation with the activity and severity of periodontal disease." (PMID 39456446, 2024). "The levels and especially activation of MMP-8, MMP-9, and MMP-13 have been shown to be correlated with active stages of periodontal disease, and they decrease to levels found in periodontally healthy GCF after conventional periodontal treatment." (PMID 30669541, 2019). "The amount of IL-1, IL-8, MMP-8, MMP-9, and MMP-13 in saliva samples from patients with periodontal disease and healthy controls have been analyzed and compared, and one study compared hemoglobin levels in blood samples with biomarkers in saliva samples from patients with periodontal disease." (PMID 34199256, 2021). "In the present study, our findings showed that the expression levels of MMP-13 mRNA and protein were up-regulated in hPDLFs after IL-12 treatment, which suggests that the increase of MMP-13 expression may be a crucial step in the deterioration of periodontal disease." (PMID 29054963, 2017). "Because type I collagen is the major component of the periodontal extracellular matrix, special attention has been paid to the role of collagenases, especially MMP-8 and MMP-13 and gelatinases, MMP-2 and MMP-9, in periodontal diseases." (PMID 35163727, 2022). "Doxycycline hyclate is a low-dose tetracycline analog lacking antimicrobial activity, and it is indicated for the treatment of periodontal disease, acting by inhibiting the mechanisms of the MMP-8 and MMP-13 protease." (PMID 35163727, 2022).
nasopharyngeal carcinoma (10 papers, 2020 to 2025). A carcinoma arising from the nasopharyngeal epithelium. "In nasopharyngeal carcinoma, exosomes are highly enriched in intercellular adhesion molecule-1 (ICAM-1), CD44 variant isoform 5 (CD44v5) and matrix metalloproteinase 13 (MMP-13), in contrast, angio-suppressive protein TSP-1 is downregulated in these exosomes." (PMID 38200509, 2024). "Similarly, EVs derived from nasopharyngeal cancer (NPC) cells were shown to contain matrix metalloprotease 13 (MMP-13) on the EV surface." (PMID 36829629, 2023). "Additionally, exosomes containing matrix metalloproteinase-13 (MMP13) promote nasopharyngeal carcinoma cells metastasis through the degradation of the extracellular matrix (ECM)." (PMID 32426106, 2020). "For example, EVs derived from hypoxic nasopharyngeal carcinoma (NPC) cells contain MMP-13 as cargo, and treatment of normoxic NPC with hypoxic NPC-derived EVs resulted in a 2.5-fold increase in cellular expression of MMP-13." (PMID 36829629, 2023). "Moreover, ChIP assays demonstrated an HRE site in the MMP-13 promoter for HIF-1α binding in human nasopharyngeal carcinoma (NPC) CNE2 cells." (PMID 38069210, 2023). "In nasopharyngeal carcinoma (NPC) cells, hypoxic exosomes carry MMP-13, which significantly upregulates the expression of vimentin in recipient cells and reduces the level of E-cadherin, thereby promoting the EMT of NPC cells and enhancing their migratory and invasive abilities." (PMID 35359397, 2022). "HIF-1α depletion in nasopharyngeal carcinoma (NPC) cells leads to reduced MMP-13 in exosomes; in contrast, MMP-13 is overexpressed in exosomes under hypoxia, enhancing tumor cell migration and invasion." (PMID 40534881, 2025). "Apart from the SNAIL protein superfamily, other transcription factors, such as matrix metalloproteinase-13 (MMP-13), are carried in hypoxic exosomes in nasopharyngeal carcinoma (NPC) cells." (PMID 37046817, 2023).
COVID-19 (9 papers, 2021 to 2025). A disease caused by infection with severe acute respiratory syndrome coronavirus 2. "DPPIV, MMP-8, MMP-9, and MMP-13 levels decreased across COVID-19 variants, suggesting a reduced proteolytic and inflammatory response, consistent with Omicron’s lower severity compared to Alpha." (PMID 40557167, 2025). "Metalloproteases are associated with COVID-19 pathology, such as the MMP13 that reduces repair during viral infection in bronchial epithelial cells." (PMID 40980495, 2025). "Besides MMP-9, which has been shown to be associated with a high risk of mortality, others, such as MMP-1, MMP-2, MMP-8, and MMP-13 have also been correlated with disease severity and increased risk of death, especially during the acute phase of COVID-19." (PMID 37372128, 2023). "Further, the MMP-13 is associated with growth arrest DNA damage (GADD45/MMP13) and may be responsible for causing the COVID-19 associated coagulopathy (CAC) in susceptible human subjects." (PMID 38077924, 2023). "MMP-13, called collagenase, was also identified as participating in the alterations resulting from COVID-19." (PMID 37372128, 2023). "In severe cases of COVID-19, an increased expression of MMP-13 levels in epithelial cells of bronchoalveolar lavage fluid was evidenced compared to mild cases of this disease." (PMID 37372128, 2023). "In addition, power calculations were carried out to determine the ability of MMPs (MMP8, MMP12, MMP13) to distinguish MIS-C from acute COVID-19 and other tropical diseases." (PMID 36544496, 2022). "A combination of 3 MMPs (MMP-8, MMP-12 and MMP-13) produced an area under the curve (AUC) of 0.89–1, indicating that these MMPs could distinguish MIS-C from acute COVID-19 with 83–92% sensitivity and 80–85% specificity." (PMID 36544496, 2022). "Indeed, epithelial cells from bronchoalveolar lavage fluid (BALF) on severe COVID-19 showed elevated frequencies of MMP-7+ and MMP-9+ and a tendency to increase portions of MMP-2+ and MMP-13+ compared to mild cases." (PMID 35625532, 2022).
esophageal squamous cell carcinoma (9 papers, 2010 to 2024). Esophageal squamous cell carcinoma (ESCC) is a type of esophageal carcinoma (EC) that can affect any part of the esophagus, but is usually located in the upper or middle third. "We previously identified that serum EFNA1 and MMP13 were potential biomarker for early detection of esophageal squamous cell carcinoma." (PMID 38987376, 2024). "Serum MMP-13 levels were found to be uncorrelated with age and gender in patients with esophageal SCC." (PMID 34266392, 2021). "Serum MMP-13 levels have been shown to predict survival in patients with esophageal SCC, but their diagnostic value for cSCC has not been explored." (PMID 34266392, 2021). "Moreover, it was demonstrated that the overexpression of MMP13 in esophageal squamous cell carcinoma could promote cancer cell aggressiveness." (PMID 31304688, 2019). "At the same time, knockdown of MMP-13 could dramatically downregulate the migration of ESCC (esophageal squamous cell carcinoma) cells." (PMID 32711573, 2020). "Metallopeptidase 13 (MMP13), a well-known and highly regulated zinc-dependent MMP collagenase, plays a crucial part in development and progression of esophageal squamous cell carcinoma (ESCC)." (PMID 27245877, 2016). "Again, MMP-13 and TGFBI expression is elevated in esophageal squamous cell carcinoma." (PMID 25369402, 2014). "AJUBA promotes the migration and invasion of esophageal squamous cell carcinoma cells (ESCC) through the up-regulation of matrix metalloproteinase 10 (MMP10) and MMP13 expression in ESCC." (PMID 31262974, 2019).
head and neck squamous cell carcinoma (9 papers, 2004 to 2026). A squamous cell carcinoma that arises from any of the following anatomic sites: lip and oral cavity, nasal cavity, paranasal sinuses, pharynx, larynx, and salivary glands. "MMP13 was suggested to be associated with advanced local invasion and aggressiveness in oral and head and neck squamous cell carcinoma." (PMID 33076370, 2020). "MMP-7 and MMP-13, which are upregulated in the human head and neck squamous cell carcinoma OSC-20 cell line, can cleave PD-L1, whereas inhibitors that specifically target MMP-13 are able to restore mPD-L1 expression." (PMID 35386715, 2022). "MMP7, MMP9, MMP11, MMP12 and MMP13 were all up-regulated in head and neck squamous cell carcinoma." (PMID 36941602, 2023).
oral squamous cell carcinoma (9 papers, 2012 to 2025). "In cancerogenesis, upregulation of Mmp13 is associated with poor prognosis in oral squamous cell carcinoma." (PMID 37701782, 2023). "Therefore, this study aims to determine the copy number, mRNA, and protein expression of MMP13 in oral squamous cell carcinoma (OSCC) and to associate these expressions with clinicopathological parameters." (PMID 25401159, 2014). "Second, the organism is enriched in the saliva of oral squamous cell carcinoma patients, where it may foster tumorigenesis through MMP-13 up-regulation." (PMID 41471248, 2025). "MMP-13 is an essential protein involved in tumor invasion and metastasis and its expression may help predict the response to RT and prognosis in patients with oral squamous cell carcinoma." (PMID 31726667, 2019). "This indicates the proteolytic activity of MMP-13 in destroying ECM and basement membrane, which promotes oral squamous cell carcinoma development and invasion." (PMID 36505148, 2022). "Oral squamous cell carcinoma cells transfected with miR-100 may modify the expression of a number of oncogenes including ID1, EGR2, MMP13, and FGFR3." (PMID 23173870, 2012).
osteoporosis (9 papers, 2015 to 2025). A condition of reduced bone mass, with decreased cortical thickness and a decrease in the number and size of the trabeculae of cancellous bone (but normal chemical composition), resulting in increased fracture incidence. "These inhibitor experiments thus confirmed our mutant analysis and demonstrate that the medaka model can be used for future screening of compounds that interfere with Mmp13 activity to potentially prevent osteoporosis or tumor-caused osteolysis." (PMID 35281094, 2022). "While Mmp2-null mice have osteoporosis, Mmp9-null and Mmp13-null mice exhibit enlarged hypertrophic zones and osteopetrosis." (PMID 28158191, 2017). "Interestingly, IMB-R38 treatment significantly decreased mRNA levels of Mmp9, Mmp13, Mmp2, and Il-6, which play a vital role in both osteoporosis and inflammation." (PMID 41465573, 2025). "MMP-13, on the other hand, showed increased serum levels in the osteopenia patient group compared to healthy controls, while the concentrations were equalized relative to the osteoporosis group." (PMID 38138968, 2023). "In a group of women with osteopenia, MMP-13 again negatively correlated with E2 levels, as well as with CTX levels Interestingly, a 6-month therapeutic course with recombinant human parathormone among women with osteoporosis clearly reduced serum MMP-13 levels by almost 37%." (PMID 38138968, 2023). "In experimental glucocorticoid-induced osteoporosis and osteocytic osteolysis, these three enzymes are upregulated in the trabecular bone of the metaphysis whereas MMP-2 and MMP-13 are expressed in the cortical bone diaphysis." (PMID 32116759, 2020). "Our study revealed 72 targets between DHT and osteoporosis, including CTSK, MMP13, MAPK14, CASP3, etc., suggesting that these targets are principally related to the inflammatory response, apoptosis, and oxidative stress, which is consistent with the results of GO and KEGG analyses." (PMID 36210855, 2022). "In contrast, hyperglycemia could lead to increased alkaline phosphatase expression and suppressed Osteocalcin, MMP-13, VEGF, and GAPDH levels in osteoblasts resulting in osteoporosis." (PMID 25742620, 2015). "In addition, MMP-13 was negatively correlated with BALP, estradiol (E2), and OPGL levels, and positively correlated with OPG, PINP, and runt-related transcription factor 2 (Runx2) among patients with osteoporosis." (PMID 38138968, 2023). "We selected matrix metalloproteinase-13 (MMP13) and a disintegrin and metalloproteinase with thrombospondin motifs-4 (ADAMTS4) as representatives of collagenases and aggrecanases, respectively, and included samples from patients with osteoporosis (OP) for comparison." (PMID 34829822, 2021).
Stroke (9 papers, 2013 to 2022). Sudden impairment of blood flow to a part of the brain due to occlusion or rupture of an artery to the brain. "MMP‐13 would appear therefore to modulate the architecture of thrombi around the site of plaque rupture to increase risk of stroke." (PMID 31894636, 2020). "MMP‐13 would appear therefore to modulate the architecture around sites of infarction to increase both risk of stroke and its hemorrhagic complications." (PMID 30046741, 2018). "Our data suggest a VWF‐mediated role for MMP‐13 in the recruitment of platelets to the site of vascular injury and may provide new insights into the association of MMP‐13 in atherothrombotic and stroke pathologies." (PMID 31894636, 2020). "The most significantly upregulated genes, including Lpl, Spp1, Cd36, Mmp2, and Mmp19, and the most highly enriched genes, including Cd5l, Mmp3, Mmp12, and Mmp13, indicate a pronounced disturbance in lipid homeostasis in infarcts at 7 weeks after stroke." (PMID 34819339, 2022). "First-ever ischemic stroke patients enrolled in intensive rehabilitation study demonstrated that MMP levels were stable as healthy volunteers during the study period but baseline MMP-12 and MMP-13 were correlated with stroke severity." (PMID 31291966, 2019). "At concentrations comparable to those reached in stroke patient plasma and found to correlate with severity of infarction, MMP‐13 can interact with both GPVI and αIIbβ3, and can compete with CRP and fibrinogen for occupation of these receptors." (PMID 30046741, 2018). "High levels of both MMP-9 and MMP-13 were detected in the hyperacute phase of stroke and were correlated with an increase in diffusion-weighted imaging lesions within the first 24 h." (PMID 23565108, 2013). "MMP-13 has also been shown to be involved in tissue injury after stroke." (PMID 23565108, 2013). "miR-320 targets ETS2, a transcription factor that regulates the expression of several genes important to leukocyte extravasation post-stroke including MMP-9, MMP-3, MMP-13, ANGPT1, and TNF." (PMID 24911610, 2014). "Moreover, following stroke, alterations in other MMPs such as enhanced levels of pro/active MMP-2, MMP-3, MMP-10, and MMP-13 have been reported." (PMID 31291966, 2019). "Priming of 3D-MSC spheroids leads to increased levels of MMP-13, particularly after treatment with IL-1β, and so may not have a therapeutic benefit if given in the acute phase after stroke." (PMID 29343288, 2018).
Sepsis (8 papers, 2013 to 2023). Sepsis is defined as life-threatening organ dysfunction caused by a dysregulated host response to infection. "MMP13 has been implicated in the pathogenesis of multiple disorders such as sepsis, joint diseases, tumor invasion and metastasis, and asbestos-induced lung disease." (PMID 37207229, 2023). "However the mechanism by which carriers of the AA genotype and the A allele of this MMP-13 SNP develop more easily sepsis is not well understood." (PMID 24833564, 2014). "The association of the MMP-1 (-1607 1G/2G) SNP and sepsis might be due to linkage disequilibrium with the MMP-13 SNP because the MMP-13 and MMP-1 genes are both located in the same cluster of the chromosome 11q22-23 along with the MMP-3, MMP-7, MMP-8, MMP-10, MMP-12, and MMP-20 genes." (PMID 24833564, 2014). "MMP13 has previously been found to be upregulated in preclinical models of sepsis; however, the source of MMP13 in these studies appeared to be epithelial cells and inflammatory cells." (PMID 37175585, 2023). "MMP-9, TIMP-2 and TIMP-1 have been shown to be elevated in patients with severe sepsis and septic shock as well as in animal models of endotoxemia, while MMP-1, MMP-8 and MMP-13 have also been associated with sepsis." (PMID 30466423, 2018). "We report here for the first time an association between the MMP-13 (−77 A/G) and the MMP-1 (−1607 1G/2G) SNPs and sepsis." (PMID 24833564, 2014). "In conclusion, we report for the first time an association between the MMP-13 and the MMP-1 SNPs and sepsis, as well as an independent association of plasma MMP-8 and MMP-9 levels with sepsis." (PMID 24833564, 2014). "We observed that MMP13−/− mice display a strong protection in LPS- and caecal ligation and puncture-induced sepsis." (PMID 23723167, 2013). "We report for the first time an association between MMP-13 and MMP-1 SNPs and sepsis." (PMID 24833564, 2014). "In conclusion, our results suggest that MMP13 is a potential therapeutic target for treatment of inflammatory disorders associated with TNF-dependent dysfunction of the intestinal barrier, such as sepsis and IBD." (PMID 23723167, 2013). "We identified MMP13 as an important mediator in sepsis and IBD via the shedding of TNF." (PMID 23723167, 2013). "Our results suggest that MMP13 is a potential therapeutic target for treatment of inflammatory disorders associated with TNF-dependent dysfunction of the intestinal barrier, such as sepsis and IBD." (PMID 23723167, 2013). "We also subjected MMP13+/+ and MMP13−/− mice to caecal ligation and puncture (CLP), the gold standard model for human sepsis, and this revealed that MMP13−/− mice are also significantly protected against CLP-induced death." (PMID 23723167, 2013). "We bring forward now the potential role of collagenases (MMP-13 and MMP-1) and perhaps stromelysins (MMP-3) in sepsis, an interesting finding because these MMPs are neither expressed in neutrophils nor released from neutrophils granules after endotoxin challenge as MMP-8 and MMP-9 do5." (PMID 24833564, 2014).
Hyperglycemia (7 papers, 2015 to 2024). An increased concentration of glucose in the blood. "Previous studies have reported that glucose neurotoxicity is caused by the increased expression of MMP13 with the formation of H2O2 due to hyperglycemia." (PMID 39456763, 2024). "Bindarit, the small molecule that specifically inhibits the synthesis of MCPs, reversed the effect of hyperglycemia on the expression of Oc and Mmp13." (PMID 35743867, 2022). "Another study also demonstrated that hyperglycemia induced the protein expression of COX-2 and the production of PGE2, IL-6 and MMP-13, and concomitantly decreased the protein expression of type 2 collagen in human chondrocytes." (PMID 38339087, 2024). "In summary, the present study demonstrates that in type-1 diabetic kidney, hyperglycemia results in the downregulation of PPARγ and the upregulation of RXRα, RXRβ and RARγ1, which possibly contributes to elevated PAI-1 levels, and thus, elevated MMP-9 and MMP-13." (PMID 34680110, 2021).